CCAR1 (cell division cycle and apoptosis regulator 1)
Diseases named in the same sentence as CCAR1 in open-access papers (continued):
Sharing a sentence is not in itself a finding about the gene and the disease.
cervical cancer (1 paper, 2022). A primary or metastatic malignant neoplasm involving the cervix. "Our study is the first to validate an interaction between CCAR1 and Kpnβ1, and to show that this interaction is enhanced in cancer, particularly in HeLa cervical cancer cells." (PMID 36418423, 2022).
diffuse large B-cell lymphoma (1 paper, 2025). "In addition, the strong positive correlation between STK33 and CCAR1 expression was also observed in liver hepatocellular carcinoma and diffuse large B‐cell lymphoma." (PMID 40908551, 2025).
glioblastoma (1 paper, 2024). The most malignant astrocytic tumor (WHO grade IV). "To further validate whether PDIA5 influences glioblastoma malignancy through CCAR1 in vivo, we injected stable transfected U87 cell lines (shCtrl, shPDIA5-1, shPDIA5-2, shPDIA5-1+LV-CCAR1 and shPDIA5-2+LV-CCAR1) into the brain of nude mice using a stereotaxic instrument to form intracranial GBMs." (PMID 39247813, 2024).
Huntington disease (1 paper, 2018). Huntington disease (HD) is a rare neurodegenerative disorder of the central nervous system characterized by unwanted choreatic movements, behavioral and psychiatric disturbances and dementia. "To observe the impact of CCAR‐1 on proteostasis, we used a C. elegans Huntington's disease model to observe polyglutamine aggregate formation and toxicity in response to ccar‐1 RNAi." (PMID 30003683, 2018). "CCAR‐1 therefore normally decreases proteostasis in a C. elegans Huntington's disease model." (PMID 30003683, 2018).
juvenile dermatomyositis (1 paper, 2024). Juvenile dermatomyositis (JDM) is the early-onset form of dermatomyositis (DM), a systemic, autoimmune inflammatory muscle disorder, characterized by proximal muscle weakness, evocative skin lesion, and systemic manifestations. "Anti-CCAR1 autoantibody frequency was 9% of an anti-TIF1γ positive US juvenile dermatomyositis (JDM) cohort screened by ELISA, and was associated with a lower frequency of cutaneous ulceration and similar clinical features to anti-Sp4 autoantibodies." (PMID 39514366, 2024).
myositis (1 paper, 2024). "We aimed to determine the frequency of anti-Sp4 and anti-CCAR1 in UK anti-TIF1γ-positive myositis populations and report any observed clinical associations, including cancer risk." (PMID 39514366, 2024). "This study aims to identify the frequency of anti-Sp4 and anti-CCAR1 in adult and juvenile UK anti-TIF1γ-positive myositis populations and report clinical associations." (PMID 39514366, 2024). "Two of eight of the anti-CCAR1 autoantibody positive adult myositis patients had cancer, which is similar to the rate of cancer in patients with anti-TIF1γ alone." (PMID 39514366, 2024). "Anti-Sp4 and anti-CCAR1 autoantibodies are less common in the adult UK anti-TIF1γ-positive myositis population compared with published data from the USA, limiting their use as biomarkers for cancer risk." (PMID 39514366, 2024). "We were surprised therefore to observe a much lower frequency of anti-Sp4 and anti-CCAR1 autoantibodies in UK adult anti-TIF1γ positive myositis participants." (PMID 39514366, 2024). "Nineteen (37%) anti-TIF1γ positive UK adult myositis patients had cancer; neither of the two patients with anti-Sp4 autoantibodies and 25% (2/8) of anti-CCAR1 autoantibody-positive patients had cancer." (PMID 39514366, 2024).
oesophageal cancer (1 paper, 2022). "We also show increased levels of endogenous CCAR1 in cervical and oesophageal cancer cell lines compared to normal." (PMID 36418423, 2022). "However, no reports have yet described the expression or role of CCAR1 in cervical or oesophageal cancer." (PMID 36418423, 2022).
osteosarcoma (1 paper, 2024). A usually aggressive malignant bone-forming mesenchymal neoplasm, predominantly affecting adolescents and young adults. "The model includes seven genes, with CCAR1 and C1QTNF1 increasing of CCAR1 and connected with an increased risk of osteosarcoma as risk factor, while increased expression of DOK3, RBMXL1, HS3ST2, SCL18B1, and ATP6VOD1 as protective factors." (PMID 38586328, 2024).
Stroke (1 paper, 2020). Sudden impairment of blood flow to a part of the brain due to occlusion or rupture of an artery to the brain. "Overexpression of Ccar1 has been shown to lead to increased apoptosis, suggesting its role in cell death post-stroke." (PMID 32315348, 2020).
cancer (27 papers, 2012 to 2025). A tumor composed of atypical neoplastic, often pleomorphic cells that invade other tissues. "Due to the small numbers of anti-CCAR1 and anti-Sp4 autoantibodies identified, this study is underpowered to draw firm conclusions on the influence of these autoantibodies on cancer risk and other clinical features." (PMID 39514366, 2024). "Two novel autoantibodies, anti-Sp4 and anti-CCAR1, have recently been described which co-occur with anti-TIF1γ and significantly attenuate the cancer risk to a level comparable to that of the general population." (PMID 39636383, 2024). "Results reported in different studies show that autoantibodies against Sp4 and CCAR1 are associated with a reduced risk of cancer in adults with anti-TIF-1γ -positive DM." (PMID 39169942, 2024). "Consistent with our findings, high expression of CCAR1 is associated with cancer occurrence and development." (PMID 37347215, 2023). "In the Stanford cohort, anti-CCAR1 autoantibodies were significantly negatively associated with a diagnosis of cancer within 3 years of first DM symptom (OR 0.27 [95% CI 0.7–1.00], P = 0.050)." (PMID 35040440, 2022). "Patients with the sole presence of anti–TIF1-γ had a two- to four-fold higher incidence of cancer, whereas anti-CCAR1 antibodies were negatively associated with cancer within three years of diagnosis (OR 0.27, P = 0.05 [Stanford]; OR 0.13, P = 0.008 [Johns Hopkins])." (PMID 35040442, 2022). "We considered the possibility that our data pertaining to stage could be a result of anti-CCAR1–associated cancers being enriched for types that typically present at an earlier stage." (PMID 35040440, 2022). "Autoantibodies recognizing cell division cycle and apoptosis regulator protein 1 (CCAR1) were the most frequent, and were significantly negatively associated with contemporaneous cancer (discovery cohort OR 0.27 [95% CI 0.7–1.00], P = 0.050; validation cohort OR 0.13 [95% CI 0.03–0.59], P = 0.008)." (PMID 35040440, 2022). "Anti-CCAR1 antibodies were negatively associated with cancer emergence within 3 years of DM onset." (PMID 35040440, 2022). "Similarly, in the Johns Hopkins cohort, anti-CCAR1 autoantibodies were significantly negatively associated with a history of cancer within 3 years (OR 0.13 [95% CI 0.03–0.59], P = 0.008)." (PMID 35040440, 2022). "To further explore the underlying mechanism of DCLK1‐mediated cancer stemness and 5‐fluorouracil resistance, we identified CCAR1 as a protein interacting with DCLK1, and elucidated that the C‐terminal domain (Pro301 to Met729) of DCLK1 was indispensable for interacting with CCAR1." (PMID 35522902, 2022). "Interestingly, the co-expression of certain antibodies—particularly anti-CCAR1 (cell division cycle and apoptosis regulator 1) alongside anti-TIF1γ—may reduce cancer risk to levels comparable to the general population." (PMID 40943714, 2025). "Prior studies have reported the involvement of CCAR1 in cell proliferation and apoptosis across various cell lines, including cancer cells." (PMID 40130381, 2025). "Anti-TIF1γ autoantibodies are strongly associated with cancer and often co-occur with autoantibodies against other proteins such as SP4 and CCAR1." (PMID 40568657, 2025). "Previous studies have shown that CCAR1 can interact with β-catenin in human clonal carcinoma cells and enhance its ability to activate transfected reporter genes." (PMID 40978202, 2025). "CCAR1 is a cyclin, and inhibition of its expression can suppress the proliferation and migration of cancer cells." (PMID 38509306, 2024). "In the process of chemotherapy-induced cancer cell apoptosis, CCAR1 is also one of the essential proteins involved 43,44." (PMID 39247813, 2024). "In HCC, the interaction of CCAR1 with β-catenin induces cancer stem cell enrichment via activation of Wnt target genes." (PMID 37173882, 2023). "A total of 10 anti-CCAR1–positive patients with cancer met these criteria, 9 of whom had staging data." (PMID 35040440, 2022).
cancer (continued). "Although the numbers were small, these data showed that cancers were diagnosed later in anti-CCAR1–positive patients than their anti-CCAR1–negative counterparts (median time from DM onset 4.3 vs. 0.85 years, respectively; P = 0.006)." (PMID 35040440, 2022). "In the current study, we applied DCLK1‐IN‐1 to targeting DCLK1, and found that DCLK‐IN‐1 suppressed 5‐fluorouracil resistant CRC cells by inhibiting CCAR1/β‐catenin pathway‐mediated cancer stemness." (PMID 35522902, 2022). "If cancer was ultimately diagnosed in patients with DM and anti-CCAR1 autoantibodies, cancers were of a lower stage and occurred further from DM diagnosis (4.3 vs. 0.87 years)." (PMID 35040442, 2022). "Western blot analysis was first performed to analyse levels of endogenous CCAR1 and FUBP1 in normal and cancer cells lines, and results revealed increased expression of both CCAR1 and FUBP1 in cancer cells compared to normal." (PMID 36418423, 2022). "When cancer did emerge, it occurred significantly later in anti-CCAR1–positive compared with anti-CCAR1–negative patients (median time from DM onset 4.3 vs. 0.85 years, respectively; P = 0.006)." (PMID 35040440, 2022). "The decreased frequency of cancer observed in anti-CCAR1–positive patients was present across multiple cancer types, suggesting that the effect is not limited to a particular tumor type or mechanism." (PMID 35040440, 2022). "Collectively, these data suggested that targeting DCLK1 suppressed 5‐fluorouracil resistant CRC cells through inhibiting CCAR1/β‐catenin pathway‐mediated cancer stemness." (PMID 35522902, 2022). "Mechanistically, we elucidated that DCLK1 promoted 5‐fluorouracil resistance in CRC by CCAR1/β‐catenin pathway‐mediated cancer stemness." (PMID 35522902, 2022). "In this context, we propose that immunization with linked sets of antigens (e.g., TIF1-γ, CCAR-1, or the other autoantigens) associated with cancer protection as defined in this study might be harnessed in novel prevention and therapeutic approaches to cancer, particularly in high-risk groups." (PMID 35040440, 2022). "Herein, we highlighted a mechanism linking a CSCs maker DCLK1 and 5‐fluorouracil resistance, and demonstrated that DCLK1 inhibitor suppressed 5‐fluorouracil resistant CRC cells through inhibiting CCAR1/β‐catenin pathway‐mediated cancer stemness." (PMID 35522902, 2022). "For instance, circZKSCAN1 negatively regulates cancer stem cells by physically binding FMRP against the CCAR1 complex in HCC." (PMID 33679871, 2020). "circZKSCAN1 negatively regulates cancer stem cells by physically binding FMRP against CCAR1 complex." (PMID 33679871, 2020). "This review focuses on the background and pleiotropic roles of CARP-1/CCAR1 as well as its apoptosis signaling mechanisms in response to chemotherapy in cancer cells." (PMID 25894788, 2015). "Overall, it is increasingly becoming evident that CARP-1/CCAR1 also functions as a tumor suppressor and/or mediator of apoptosis in diverse cancers." (PMID 25894788, 2015). "This discrepancy may reflect context-dependent functions of Ccar1, varying between cancer cells and pluripotent stem." (PMID 40978202, 2025). "Moreover, circRNAs have been shown to negatively regulate cancer stem cells in HCC by physically binding to the CCAR1 complex through FMRP." (PMID 40130381, 2025). "In addition, they found that DCLK1 positively regulates β-catenin signaling through CCAR1, which is responsible for the maintenance of cancer stem cells." (PMID 40978202, 2025). "Importantly, they showed that DCLK1 inhibitor can block cancer stem cells mediated by the CCAR1/β-catenin signaling pathway and thus suppress 5-fluorouracil-resistant CRC cells in vitro and in vivo." (PMID 40978202, 2025). "Notably, the STK33 expression was found to be correlated with poor prognosis in TNBC, which promotes cancer cell proliferation and migration via the CCAR1/β‐catenin pathway." (PMID 40908551, 2025).
cancer (continued). "While anti-CCAR1 and anti-Sp4 appear to be the most common ‘cancer-modifier’ autoantibodies in anti-TIF1γ-positive DM, others have been described and an increasing diversity of the autoimmune response appears to be associated with a reduced likelihood of cancer emergence." (PMID 39636383, 2024). "Therefore, our findings suggested that DCLK1 promoted 5‐fluorouracil resistance in CRC by CCAR1/β‐catenin pathway‐mediated cancer stemness." (PMID 35522902, 2022). "It is also possible that anti-CCAR1 autoantibodies might be inhibiting a cancer-promoting function of anti–TIF1-γ." (PMID 35040440, 2022). "Later appearance and less advanced stage in cancers from anti-CCAR1–positive patients." (PMID 35040440, 2022). "Moreover, we find that DCLK1 positively regulates β‐catenin signalling via CCAR1, which is responsible for maintaining cancer stemness." (PMID 35522902, 2022). "Interestingly, chemical inhibitors of CCAR1 function have been shown to negatively affect the viability of multiple types of cancer." (PMID 35040440, 2022). "Therefore, our findings reveal that DCLK1 promotes 5‐fluorouracil resistance in CRC by CCAR1/β‐catenin pathway‐mediated cancer stemness." (PMID 35522902, 2022). "The increased statistical power afforded by this enabled us to address whether the stage of the cancer or time to cancer diagnosis after DM onset differed in anti-CCAR1–positive versus anti-CCAR–negative patients." (PMID 35040440, 2022). "Having proved that DCLK1 promoted 5‐fluorouracil resistance through CCAR1/β‐catenin pathway‐mediated cancer stemness, we wondered whether targeting DCLK1 could suppress 5‐fluorouracil resistant CRC cells." (PMID 35522902, 2022). "For anti-CCAR1, which is also frequently targeted but is less frequently mutated in cancer (2.1% of cancers in COSMIC), the observations here that CCAR1 and TIF1-γ are in a molecular complex strongly indicate that CCAR1 is targeted through intermolecular spreading." (PMID 35040440, 2022). "Thus, significant investigations suggest that CARP-1/CCAR1 plays important roles in regulating cancer cell growth in part by recruiting multiple mediators and confers optimal conformation for transcriptional functions of NRs." (PMID 25894788, 2015). "Furthermore, increasing research suggests that CCAR1 may play an important role in the malignant progression of cancers." (PMID 39247813, 2024). "Importantly, we demonstrated that DCLK1 inhibitor could block CCAR1/β‐catenin pathway‐mediated cancer stemness and consequently suppressed 5‐fluorouracil resistant CRC cells in vitro and in vivo." (PMID 35522902, 2022). "In neither cohort was an association between anti-CCAR1 and any specific cancer type present." (PMID 35040440, 2022). "We observed that cancers were sometimes diagnosed in anti-CCAR1–positive patients (10 in the Johns Hopkins cohort, 8 in the Stanford cohort), and wondered whether these cancers have similar timing of diagnosis and cancer stage as those cancers diagnosed in anti–TIF1-γ–only DM patients." (PMID 35040440, 2022). "Anti-CCAR1 was therefore prioritized for initial studies to investigate whether the presence of additional antibodies influenced the frequency of cancer diagnosis in anti–TIF1-γ–positive DM patients (the other specificities are addressed in the last part of the Results section)." (PMID 35040440, 2022). "Importantly, we demonstrate that DCLK1 inhibitor could block CCAR1/β‐catenin pathway‐mediated cancer stemness and consequently suppresses 5‐fluorouracil resistant CRC cells in vitro and in vivo." (PMID 35522902, 2022). "Similarly, how anti-CCAR1 antibodies modulate cancer growth needs further investigation." (PMID 35040442, 2022). "Interestingly, rare cancers nevertheless did occur in the anti-CCAR1–positive group, giving us the opportunity to ask whether there was anything distinct about cancers emerging in the setting of the combined immune response." (PMID 35040440, 2022).